CSDE1 (cold shock domain containing E1)
Diseases named in the same sentence as CSDE1 in open-access papers (continued):
Sharing a sentence is not in itself a finding about the gene and the disease.
infection (3 papers, 2023 to 2025). The state of being infected such as from the introduction of a foreign agent such as serum, vaccine, antigenic substance or organism. "Consistent with the in vitro results, infections in CSDE1 KD cells resulted in shorter poly(A)-tail lengths compared to infections in control cells." (PMID 41279592, 2025). "To this end, we knocked down CSDE1 using CRISPRi with two independent guide RNAs and used an RNAse H northern blot to analyze the tail-length distribution of viral mRNAs at each passage of a 5-passage serial infection." (PMID 41279592, 2025). "We next returned to our original serial infection scheme and tested whether CSDE1 has a role in the poly(A)-tail length distribution of viral mRNAs in infected cells." (PMID 41279592, 2025). "For the CSDE1 KO and GOLGA7 KO cells, an intermediate CHIKV replication phenotype was observed: CHIKV RNA abundance increased over the course of the infection time course, but it remained well below the levels measured in the NT control cells." (PMID 41372121, 2025). "Interestingly, although the poly(A)-tail lengths of viral mRNAs were consistently shorter in CSDE1 KD cells, the extent of poly(A)-shortening was not exacerbated as infection passages increased, suggesting that a new steady-state is achieved during the first passage." (PMID 41279592, 2025).
CSDE1 also shares sentences with these, for which no sentence is quoted: paraganglioma (4 papers); congenital anemia (2); gastric cancer (1); hepatocellular carcinoma (1); Huntington disease (1); neurodevelopmental disorder (1); neuroendocrine tumors (1); ovarian carcinoma (1); pancreatic adenocarcinoma (1); Parkinson disease (1); skin cancer (1); superficial spreading melanoma (1); thalassemia (1).